CRP (C-reactive protein)
Diseases named in the same sentence as CRP in open-access papers (continued):
Sharing a sentence is not in itself a finding about the gene and the disease.
infection (continued). "For example, if the gradient between the latest two CRP variables were positive, it would indicate that the infection is getting worse, whereas if the gradient were negative, it would indicate infection resolution." (PMID 34207560, 2021). "C-reactive protein (CRP) is an inflammatory protein produced primarily by the liver as part of the acute phase response, which is initiated in response to changes in homeostasis due to insults such as infection or tissue injury." (PMID 33517931, 2021). "We studied clinically stable transplant recipients without acute rejection or infection in whom high Bregs were associated with high GFR, low CRP, and high drug doses." (PMID 34102006, 2021). "CRP remained completely suppressed in the D + T + group irrespective of the occurrence of a secondary infection." (PMID 34781995, 2021). "Expression of CRP is induced by IL-6 and other cytokines (IL-1β, TNF) via NF-κB and other transcription factors as part of the acute-phase response or during inflammatory conditions and infections." (PMID 34925360, 2021). "Correlation within the first CRP cluster revealed a significant relationship between IPI (no infection/infection) classification and CRP levels." (PMID 35011910, 2021). "Surgeons often use a combination of inflammatory serum biomarkers such C-reactive protein (CRP) or interleukin-6 (IL-6), synovial markers, microbiological findings and clinical factors such as wound healing to assess the resolution of infection and to guide the timing of second stage reimplantation." (PMID 33795812, 2021). "In addition to the traditional infection markers White Cell Count (WCC) and C-reactive protein (CRP), a large randomized-controlled trial in adult general ICU patients demonstrated superiority of a Procalcitonin (PCT) guided approach." (PMID 35155322, 2021). "Although some clinical symptoms such as increased body temperature and increased level of CRP were transiently observed after the second infection, all of the monkeys showed negative results of PCR in swab samples after rechallenging with SARS-CoV-2." (PMID 34625475, 2021). "In our analysis, the proportion of CM at admission was inversely correlated with CRP levels, an unspecific marker of inflammatory activity as well as with PCT, a novel biomarker with potential to differentiate between inflammation and infection." (PMID 33020969, 2021). "If CRP or PCT, predictors of infection, are positive, treatment should be given immediately." (PMID 34820395, 2021). "All subjects had normal Hb levels (13.7 ± 0.8 g dL−1) with mean ± SD serum ferritin of 25.2 ± 10.1 μg L−1 and with no infection or inflammation (mean ± SD CRP: 1.6 ± 2.1 mg L−1)." (PMID 35402470, 2021). "Elevated LDH and CRP seen in non-survivors in all groups are evidence of increased inflammation and immune response to infection." (PMID 35242818, 2021). "Setting the (individually determined) maximum CRP as day zero and 100%, the predicted one-phase decay is reached in the non-infection group and infection group with a satisfying accuracy (R2 = 0.72 and R2 = 0.83, respectively)." (PMID 34768504, 2021). "Hospitalized patients with SARS-CoV-2 infection have shown higher levels of chemokines, C-reactive protein (CRP) stimulating “cytokine storm”,characterised by significant production of IL-6, from the ongoing infection in the lungs, with sex differences existing in immune responses." (PMID 34753980, 2021). "An analysis of the ROC curve for CRP levels in the first 12 hours of life revealed no statistical significance for the diagnosis of infection in the investigated group (p = 0.18)." (PMID 34307663, 2021). "In the case of early measurements (i.e., <24 h of infection onset), PCT may perform better because its concentration may peak quicker than that of CRP." (PMID 34746044, 2021). "Many patients with MDS have non-specific symptoms and report fevers and elevated CRP that cannot be attributed to infection; we termed this group UAD." (PMID 33679746, 2021).
infection (continued). "Moreover, the SG showed more severe inflammatory markers of infection than the MG, such as WBC count (6.40 × 10∧9/L vs. 5.51 × 10∧9/L, p = 0.001), neutrophil (4.15 × 10∧9/L vs. 3.50 × 10∧9/L, p < 0.001), and CRP (7.76 vs. 3.18 mg/L, p < 0.001)." (PMID 34164413, 2021). "The decrease in CRP levels in the small intestinal wall of turkeys fed diets with the higher Lys content (NRC + 10%), noted in the present study, suggests that the immune system of turkeys effectively protected them against pathogens and infection." (PMID 34354153, 2021). "As acute phase response proteins, CRP and FIB may increase in many diseases, such as infection and autoimmune injury." (PMID 34238962, 2021). "With a continuous treatment with teicoplanin and imipenem for 15 days and intraperitoneal catheter removed, the infection symptom was improved evidenced by a normal body temperature, also with white blood cell count (WBC), procalcitonin (PCT) and C-reactive protein (CRP) dropped to normal levels." (PMID 34120601, 2021). "Serum levels of C-reactive protein (CRP) and procalcitonin (PCT) show a physiological increase during the first 48–72 h of life and are influenced by several maternal and fetal pro-inflammatory conditions, other than infections." (PMID 34830040, 2021). "It is unlikely that the effect on venular calibre reflected the different types of infections or the antibiotics themselves since venular calibre did not change where the CRP level did not fall or when different antibiotics were used." (PMID 34446820, 2021). "Third, not all studies excluded participants with suspected infection, as measured by a fixed CRP threshold." (PMID 34050185, 2021). "The only discriminant factors with statistical significance as to infection versus no infection were discharge at the wound site, fever, and elevated CRP." (PMID 33210240, 2021). "The most important APPs in ruminant animals are Hp and CRP that provide an early nonspecific defense mechanism against injury, infection, or inflammation before the response of specific immunity." (PMID 34903925, 2021). "The C-reactive protein is widely used to guide antibiotic therapy, although its increase in the first hours of life is not always evidence of infection." (PMID 33525647, 2021). "Significant discriminants between infection and no infection included fever (P = 0.041), discharge at the wound site (P < 0.0001), and elevated CRP (P = 0.042)." (PMID 33210240, 2021). "One recent study proposed that, if CRP does not fall after the third postoperative day, antibiotic treatment should be reassessed, and concomitant infections screened." (PMID 34439638, 2021). "The authors noted that presepsin may have better prognostic validity than procalcitonin, C-reactive protein (CRP) and the erythrocyte sedimentation rate (ESR), while being more specific for infection compared to both lactate and the ESR." (PMID 34150378, 2021). "The sensitivity and specificity reflected by the area under the ROC curve (AUC) showed that when infection occurred in children with INS, when one or more factors including steroid resistance, IS treatment and increased CRP were combined, a more severe infection was very likely to occur." (PMID 34336733, 2021). "As expected, when using the forced adjudication (which included patients with indeterminate infection status in performance calculations) AUROC’s for InSep, PCT, and CRP all decreased markedly ranging from 0.70 to 0.77, reflecting the inaccuracies (lack of consensus) in the ‘forced adjudication’." (PMID 34142256, 2021). "At the same time, they found that serum ESR, CRP, and interleukin 6 (IL-6) had no benefits in predicting infection persistency before second-stage prosthesis implantation." (PMID 33774699, 2021).
infection (continued). "C-reactive protein and ESR have been widely used to determine the presence of infection after total joint replacement, but appropriate quantitative interpretation of the values and trend of CRP and ESR may be difficult during the early perioperative phase." (PMID 34429835, 2021). "Otherwise the reports were not suggestive of occult infection with normal white cell count, C-reactive protein (CRP), and negative blood cultures." (PMID 33865405, 2021). "The CRP/alb ratio predicted postoperative infections also in our data, although hs-CRP was not used." (PMID 33740951, 2021). "Herein, we proposed a lateral flow assay (LFA) strip based on surface-enhanced Raman scattering (SERS) nanotags (SERS-LFA strips) for the simultaneous and quantitative detection of dual infection biomarkers, serum amyloid A (SAA) and C-reactive protein (CRP), respectively." (PMID 34198765, 2021). "The C-reactive protein (CRP) level of the VAKI group was higher than that of the non-VAKI group (5.78 ± 8.74 mg/dL vs. 2.39 ± 4.88 mg/dL; p < 0.001), whereas the CRP level of the infection subgroup was comparable to that of the VAKI group." (PMID 34199555, 2021). "Overall, these results indicate how low albumin (reflective of malnourishment, as well as infection owing to its negative acute phase protein property), high CRP, and old age correlate with inpatient mortality in an additive manner." (PMID 34207560, 2021). "Five months after the uneventful HTX, lab test of the asymptomatic patient showed moderate, increasing C-reactive protein level without obviuos source of infection." (PMID 34418979, 2021). "Moreover, non-specific inflammatory markers such as erythrocyte sedimentation rate (ESR) or C-reactive protein (CRP) levels can be elevated during the relapse of the AAV and also during infection complications of AAV treatment." (PMID 33664330, 2021). "Patients with severe infection had more increased inflammatory response, including higher white blood cell counts, lower lymphocyte and neutrophil counts, and increased C-reactive protein levels compared with the patients without severe infection (P < 0.001)." (PMID 34191844, 2021). "A comparison of receiver operating characteristic curves for PTX3, PCT, and CRP concentrations did not demonstrate any statistically significant differences in the prediction of infection in newborns (p = 0.40)." (PMID 34307663, 2021). "CRP is a helpful indicator of infection, but it is not necessarily specific and cultures are reliable tools though findings are often negative, especially in patients on antibiotics when cultures have been taken." (PMID 33470032, 2021). "No signs of infection were detected in any of the patients and CRP levels spontaneously dropped to normal values within few days." (PMID 34357446, 2021). "In order to identify variables most predictive of an infectious complication, we first identified parameters for the maximum CRP, since the maximum CRP was able to differentiate among both the non-infection vs. infection and anterolateral vs. posterior groups." (PMID 34768504, 2021). "The use of C-reactive protein testing served several purposes, such as deciding on the severity of the infection, prescribing antibiotics or not, and as a communicative tool." (PMID 34205866, 2021). "We found that baseline values of infection parameters were enriched in MV patients compared to non-MV patients, which covers CRP (p < 0.001 for survivors; p < 0.01 for non-survivors) and PCT (p < 0.05 for survivors; p < 0.0001 for non-survivors)." (PMID 34736400, 2021). "We hypothesized that PCT would be superior to CRP and WCC to diagnose infection in neonates and children treated with ECMO." (PMID 35155322, 2021). "And we did not assess the C reactive protein and leucocytes due to unavailable data regarding infection." (PMID 34537036, 2021). "A marked elevation in C-reactive protein (CRP) and procalcitonin levels in the serum may suggest an infection." (PMID 33803847, 2021).
infection (continued). "An unfavorable outcome was defined as an incomplete regression of infection (decline of C-reactive protein concentration not significant) with or without recurrent spondylodiscitis and/or unchanged or worsened neurological status without the ability to walk." (PMID 34439638, 2021). "Moreover, 12 patients transferring to the ICU had higher concentrations of infection-related biomarkers (ESR, IL2R, IL6, IP10, PCT, SF, CRP, TNFα)." (PMID 33542448, 2021). "CRP is currently used in trauma patients as a gauge for inflammation/infection, but it is understood from the literature and at the bedside that this is non-specific in the trauma cohort, who experience elevated CRP from both injury and multiple surgeries." (PMID 34065206, 2021). "C-reactive protein (CRP) is an easily measurable biomarker that reflects systemic inflammation, infection, or tissue damage in the body, and may be elevated in both acute and chronic conditions." (PMID 34194621, 2021). "No signs of infection of the surgical areas (i.e., redness, swelling, and exudate/purulence) were detected in any of the patients after laparoscopy and CRP levels spontaneously dropped to normal values within a few days and without any required treatment." (PMID 34357446, 2021). "OR, odds ratio; CI, confidence interval; SSI, surgical site infection; ICD, International Classification of Diseases; MRSA, methicillin-resistant Staphylococcus aureus; ESR, erythrocyte sedimentation rate; CRP, C-reactive protein; GPC, gram-positive cocci; GNR, gram-negative rod." (PMID 33618788, 2021). "Both CRP and ESR could be within the normal range in some patients with PJI, particularly in those with chronic and low-virulence infections." (PMID 34536150, 2021). "It is interesting to note that in SLE pleuritis CRP can be elevated also in the absence of infections." (PMID 33803847, 2021). "C-reactive protein (CRP) is a non-specific acute phase reactant elevated in infection or inflammation." (PMID 33683344, 2021). "All studies were retrospective single center studies applying different definitions of infection, they reported on one or two markers rather than comparing CRP, PCT, and WCC, and none adjusted for repeated measurements." (PMID 35155322, 2021). "In one elderly subject the third dose of 25 mg HTL0018318 was not administered due to infection-like symptoms and elevated c-reactive protein." (PMID 33883008, 2021). "All other markers (CCL4, IL-1Ra, TNF, S100A12, ferritin, C1q, CRP, and ApoA1) yielded no or hardly any detectable signals or failed to discriminate before and after infection (ApoA1, C1q)." (PMID 34943175, 2021). "Favorable outcomes were noted in patients without concomitant infections, with a normalized CRP value and in patients who received antibiotic therapy for more than six weeks (p < 0.05)." (PMID 34439638, 2021). "Serum C-reactive protein (CRP) may be altered during inflammation, infection, and tissue damage; has a short half-life; is easily accessible through blood sampling; and is useful in the sequential evaluation of inflammatory processes." (PMID 32054445, 2020). "Four patients had minimally heightened levels of leukocytes (11.2–12.4 × 103/μl), but no signs of infection (i.e., elevated C-reactive protein measures (CRP))." (PMID 32727556, 2020). "Breakthrough infection with vaccine coverage serotypes also presented with lower Hb level, higher eosinophils, and higher CRP than the non-vaccine serotype group (all p value< 0.05)." (PMID 32814590, 2020). "Multivariate GEE analysis showed that SDI, fever temperature, CRP, procalcitonin (PCT), lymphocyte percentage, NLR, hemoglobin, and renal score in SLEDAI-2k are predictive of infection (combined calculated AUC of 0.7886 and with sensitivity of 63.5% and specificity of 89.2%)." (PMID 33199770, 2020). "The levels of CRP and IL-6 can be used for indications of early stage or ruling out the infection without any delay in treatment." (PMID 32316949, 2020).
infection (continued). "The dataset did not include the results of imaging studies or markers of infection such as a complete blood count, serum lactate, C-reactive protein, or erythrocyte sedimentation rate." (PMID 33376658, 2020). "Sixteen of those patients were considered to have persistent infection, defined by the authors as discharging wound and/or increasing CRP without any other infection focus and/or local signs of infection." (PMID 32911842, 2020). "Blood tests for the C-reactive protein and WBC count were elevated and indicative of an infection." (PMID 32457718, 2020). "APPs, such as alpha 1-acid glycoprotein (AGP), transferrin (TRF), albumin (ALB) and C-reactive protein (CRP), are produced by hepatocytes as part of the innate acute phase response to trauma, infection, stress, neoplasia and inflammation, and their expressions are elevated in diarrhea." (PMID 32722717, 2020). "Changes in Alb and IgM generally involve decreases from baseline during major infections (i.e., they are negative APRs, changing with polarity opposite to APRs like CRP)." (PMID 32253915, 2020). "At that OB cut-off the diagnostic performance to discriminate severe from non-severe infection had similar sensitivity, positive predictive value and negative predictive value to C-reactive protein (CRP), but lower specificity than CRP." (PMID 33213370, 2020). "The data obtained in the present study strongly suggest that no infections occurred, as levels of CRP were within the normal levels with no significant changes noticed over the course of the experimental period." (PMID 32103450, 2020). "While the mean level of the inflammation marker CRP was within the reference range, 28% of the children had CRP levels >0.5 mg/l without clinical signs of infection." (PMID 32154197, 2020). "In all patients, high fever (more than 39 °C) and high levels of CRP (24.1 ± 7.7 mg/dL) were identified without any infection-related signs." (PMID 33122662, 2020). "C-reactive protein, non-glycosylated protein, is an important element of the innate defense system that produced from liver toward infection and stressful condition." (PMID 32368278, 2020). "Interestingly, CRP OT-I BMC have a higher number of bacteria in the mesenteric lymph nodes and the small intestine following Lm-OVA infection as compared to LMC and INS2 OT-I BMC." (PMID 32709894, 2020). "In addition, the correlation between metabolites and clinical inflammatory markers, including CRP and PCT, also provides new perspectives on infection severity evaluation." (PMID 32157124, 2020). "Min1, min2 and max2, but not aPTT, of patients with infection demonstrated weak to moderate positive correlation with CRP levels (min1: r = 0.540, p < 0.001; min2: r = 0.439, p < 0.001; max2: r = 0.340, p = 0.004; aPTT: r = 0.118, p = 0.331)." (PMID 32843693, 2020). "Patients with acute dyspnea due to an infection could be expected to show higher circulating TNFR1 and CRP levels." (PMID 32281000, 2020). "IL-6 as a biomarker for infection in EOS is not as well-known as CRP and the cut-off value for infection is uncertain." (PMID 33218324, 2020). "Our research supports the current consensus that CRP in isolation is not useful in determining the eradication of infection." (PMID 32089975, 2020). "Both CRP and procalcitonin are used for surveillance of postoperative infections after non-transplant operations." (PMID 32127631, 2020). "More than 60% of patients have elevated levels of CRP, LDH and lactic acid, which may be related to the systemic immune response induced by infection and early hypoxia in critical patients." (PMID 33009426, 2020). "In primary care, diagnostic tests are mostly used to rule out rather than rule in serious infections, and increasing the CRP cutoff would reduce its sensitivity." (PMID 31889507, 2020).